CTSS (cathepsin S)
Description:
Thiol protease. Key protease responsible for the removal of the invariant chain from MHC class II molecules and MHC class II antigen presentation. The bond-specificity of this proteinase is in part similar to the specificities of cathepsin L. Elicits itch by mediating cleavage and activation of MRGPRX1 (By similarity).
Tractability: Small molecule: a drug acting on it is in phase 2 or 3 trials; a structure with a bound ligand is known; a high-quality ligand is known; it has a high-quality binding pocket; it belongs to a druggable protein family. Antibody: UniProt places it where antibodies can reach, with high confidence; its Gene Ontology location is reachable by antibodies, with high confidence; UniProt predicts a signal peptide or a membrane-spanning region. PROTAC: ubiquitination databases record sites on it; its protein half-life has been measured; a small molecule that binds it is known.
Target class: Cysteine protease; Cysteine protease CA clan; Enzyme; Protease; Cysteine protease C1A family
Chemical probes: BI-1124 (high quality), BI-1915 (high quality), CHEMBL1209145, CHEMBL249915, PD080694, PD080873, PD080893, PD080989, PD081609, PD081686, PD081793, PD081833, PD081929, PD082094, PD082227, PD082608, PD082775, PD082887, PD082893, PD082913, and 12 more
Gene: Protein-coding gene on chromosome 1 (150,730,079 to 150,765,957, reverse strand). Ensembl gene ENSG00000163131.
Subcellular location: Lysosome; Secreted; Cytoplasmic vesicle, phagosome
Subcellular location (Human Protein Atlas): Vesicles
Pathways (Reactome):
Immune System: Endosomal/Vacuolar pathway; MHC class II antigen presentation; Neutrophil degranulation; Trafficking and processing of endosomal TLR
Cell-Cell communication: Degradation of CDH1; SRC activates STAT3 in a quantitative manner, through Cadherin-11 (CDH11), RAC1 and gp130 (IL6ST)
Extracellular matrix organization: Assembly of collagen fibrils and other multimeric structures; Degradation of the extracellular matrix
Gene Ontology:
Molecular function: collagen binding; cysteine-type endopeptidase activity; cysteine-type peptidase activity; fibronectin binding; laminin binding; protein binding; proteoglycan binding; peptidase activity; serine-type endopeptidase activity
Biological process: adaptive immune response; antigen processing and presentation of exogenous peptide antigen via MHC class II; antigen processing and presentation of peptide antigen; basement membrane disassembly; cellular response to thyroid hormone stimulus; collagen catabolic process; positive regulation of cation channel activity; protein catabolic process; protein processing; proteolysis; regulation of antigen processing and presentation; response to acidic pH; antigen processing and presentation; extracellular matrix disassembly; immune response; toll-like receptor signaling pathway; sensory perception of itch
Cellular component: extracellular matrix; extracellular region; late endosome; lysosome; phagocytic vesicle; endolysosome lumen; ficolin-1-rich granule lumen; lysosomal lumen; tertiary granule lumen; membrane
Genetic constraint (gnomAD): Loss-of-function variants: 14 observed, 32.96 expected, observed/expected ratio (o/e) 0.42, 90% interval 0.28 to 0.66. The upper end of that interval is the gene's LOEUF score, 0.66, which puts it in group 2 of 6, group 1 being the genes least tolerant of losing a copy. Missense variants: 200 observed, 334.75 expected, observed/expected ratio (o/e) 0.6, 90% interval 0.53 to 0.67. Synonymous variants: 99 observed, 120 expected, observed/expected ratio (o/e) 0.83, 90% interval 0.7 to 0.98.
Homologues: Orthologues: chimpanzee CTSS (99% identical), macaque CTSS (97% identical), rabbit CTSS (86% identical), pig CTSS (85% identical), dog CTSS (81% identical), rat Ctss (77% identical), mouse Ctss (74% identical), tropical clawed frog ctss (61% identical), zebrafish ctss2.1 (59% identical), guinea pig CTSS (58% identical), zebrafish ctss2.2 (57% identical), Caenorhabditis elegans R09F10.1 (30% identical), and 12 more. Paralogues in human: CTSK (54% identical), CTSV (50% identical), CTSL (48% identical), CTSH (36% identical), CTSF (29% identical), CTSO (27% identical), CTSC (27% identical), CTSW (26% identical), CTSB (24% identical), CTSZ (22% identical), TINAGL1 (21% identical), TINAG (18% identical).
Diseases named in the same sentence as CTSS in open-access papers:
CTSS is named in the same sentence as 325 diseases in open-access papers, as found by Europe PMC text mining. Sharing a sentence is not in itself a finding about the gene and the disease. The quoted sentences say what the papers report.
atherosclerosis (57 papers, 2011 to 2025). A disease characterized by the build-up of fatty material and calcium deposition in the arterial wall resulting in partial or complete occlusion of the arterial lumen. "Cathepsin S (CTSS) mRNA encodes a cysteine protease associated with angiogenesis and atherosclerosis." (PMID 38322593, 2024). "Both CD62E and cathepsin S (CTSS) are associated with endothelial cell activation and atherosclerosis." (PMID 37492730, 2023). "Cathepsin S–deficient mice with attenuated atherosclerosis provided convincing evidence for cysteine protease involvement in atherogenesis." (PMID 37817071, 2023). "The CTSS gene encodes cathepsin S, which influences atherosclerosis through the enzyme’s elastolysis and collagen-lysis activity." (PMID 37663249, 2023). "As a member of the cysteine protease family, CTSS (cathepsin S) levels are elevated in a variety of diseases and are strongly associated with diseases such as IgA nephropathy, diabetes mellitus and atherosclerosis." (PMID 36814902, 2023). "Attenuated atherosclerosis in cathepsin S–deficient mice provided direct evidence for cysteine protease involvement in atherogenesis." (PMID 35392813, 2022). "Cathepsin S, a proteolytic enzyme, has been reported to be associated with atherosclerosis, abdominal aortic aneurysm, cancer, obesity and type 2 diabetes." (PMID 33746900, 2021). "We recently reported that cathepsin S (CTSS), which encodes a cysteine protease associated with angiogenesis and atherosclerosis, is highly edited." (PMID 29867565, 2018). "Cathepsin S (CatS), a proteolytic enzyme, which belongs to the cysteine proteinase family, is associated with atherosclerosis, coronary heart disease, cancer and other diseases." (PMID 24223651, 2013). "The altered editing degree may regulate cathepsin S expression level by recruiting HuR protein to the 3′UTR of CTSS to stabilize the mRNA and increase the encoding level of cathepsin S to participate in the occurrence and development of atherosclerosis." (PMID 38203521, 2023). "After the establishment of atherosclerosis mouse models, gain- and loss-of-function experiments were conducted for the analysis of effects of miR-203-3p and cathepsin S on foam-cell formation, lipid accumulation, collagen deposition and serum total cholesterol." (PMID 34077394, 2021). "CTSS expressed by intimal macrophages was involved in atherogenesis, and deficiency of CTSS could reduce atherosclerosis in LDL receptor-deficient mice." (PMID 33553270, 2020). "At present, there are few studies on the relation between CTSS polymorphism and atherosclerosis." (PMID 30341237, 2018). "As the prognostic and diagnostic value of CTSS in serum levels has previously been demonstrated for pathologies such as diabetes, atherosclerosis and aortic aneurysm, we also examined CTSS secretion from these cells by measuring activities in the corresponding supernatants." (PMID 27108091, 2016). "Recent studies have identified amyloid beta, cathepsin S, and negatively charged LDL as predictors of mortality risk in atherosclerosis." (PMID 39445733, 2025). "Nicotine impairs mTORC1-mediated autophagy-lysosomal pathway, triggering TFEB nuclear translocation that elevates CTSS transcription and promotes chronic inflammation in atherosclerosis." (PMID 40692794, 2025). "Gene network analysis using the STRING database of the top 100 downregulated genes predicted novel interactions among genes such as CD4 and Beclin1 as well as CTSS, which is known to be impaired in atherosclerosis." (PMID 39120300, 2024). "CTSS degrades damaged or unwanted proteins in lysosomes, regulates antigen presentation in atherosclerosis, and mediates phagosome involvement in atherosclerosis progression through macrophages." (PMID 38764052, 2024). "The roles of CTSs in atherosclerosis were covered by a recent comprehensive article and thus will not be described in detail here." (PMID 37202785, 2023).
atherosclerosis (continued). "ADAR1 knockdown can lead to about 60% downregulation of CTSS mRNA expression, which can reduce atherosclerosis and angiogenesis in vivo." (PMID 37663249, 2023). "Accumulating evidence has confirmed the participation of CTSs in vascular diseases characterized by atherosclerosis, plaque rupture, thrombosis, calcification, aneurysm, restenosis/in-stent-restenosis, and neovasel formation." (PMID 37202785, 2023). "A pathological role for Alu editing in atherosclerosis patients related to editing in the 3’ UTR of the CTSS gene has previously been discovered." (PMID 37036839, 2023). "Previous studies have revealed that cathepsin S plays a critical role in various diseases, including atherosclerosis, abdominal aortic aneurysm, cancer, obesity and type 2 diabetes." (PMID 33746900, 2021). "Cathepsin S, as an adipokine, was reported to play a critical role in various disease, including atherosclerosis and diabetes." (PMID 33746900, 2021). "The results found high expression of cathepsin S in atherosclerosis mice and downregulation of miR-203-3p in the serum of atherosclerosis patients and ox-LDL-simulated bone marrow-derived macrophages." (PMID 34077394, 2021). "Multiple evidence demonstrated the involvement of CTSs in many cardiovascular diseases, including atherosclerosis, cardiac hypertrophy, cardiomyopathy, myocardial infarction, and hypertension, some of which are common clinical manifestations in MPSs." (PMID 32326609, 2020). "In recent years, studies have shown that CTSS plays an important role in the occurrence and development of atherosclerosis, plaque vulnerability, rupture, and the occurrence of clinical complications." (PMID 30341237, 2018). "Based on the role of CTSS in the development of atherosclerosis, we chose the CTSS rs774320676, rs768437857, rs928508030, and rs2275235 loci." (PMID 30341237, 2018). "First, TLR4 can induce the proliferation of vascular smooth muscle cells and upregulate the expression of the elastin-degrading enzyme and cathepsin S that allow smooth muscle cells to migrate to the site of atherosclerosis." (PMID 28002812, 2017). "This compound has been previously used to investigate the therapeutic potential of CTSS in atherosclerosis." (PMID 27097645, 2016). "Cathepsin S has an important role in extracellular matrix degradation and smooth muscle cells invasion thereby playing a major role in atherosclerosis as well as in angiogenesis." (PMID 24743169, 2014). "In the cathepsin enzyme family, 11 cysteinyl proteases were classified: cathepsin B, C, F, H, K, L, O, S, V, W, and Z. Cathepsin S is known for its intense elastolytic activity and plays a pivotal role in the remodeling of the arterial wall in the course of atherosclerosis." (PMID 35453881, 2022). "The present study investigated the role of CTSS in the development of atherosclerosis." (PMID 30341237, 2018). "CysC may inhibit the activity of cathepsin S and K, reduce degradation of blood vessels and vascular remodeling, and postpone the occurrence and development of atherosclerosis." (PMID 28143410, 2017). "CTSS is a lysosomal cysteine protease which is highly expressed in macrophages, has specific roles in MHC class II antigen presentation, toll-like receptor signaling and is implicated in the pathology of multiple immune disorders, including rheumatoid arthritis, emphysema and atherosclerosis." (PMID 27108091, 2016). "CTSS upregulation correlates with CPS progression, driving pathologies like atherosclerosis and muscle atrophy." (PMID 40692794, 2025). "Of these, after gene expression verification, only ITGB2, CTSS, LY86, and ITGAX were found to be highly expressed in both atherosclerosis and AAA." (PMID 39560590, 2024). "Given that the stability of RNA edits induced pro-inflammatory transcripts (such as CTSS or NEAT1) is increased in ASCVD, increased RNA editing may aid the inflammatory process of atherosclerosis." (PMID 37663249, 2023).
atherosclerosis (continued). "ADAR-mediated A-to-I RNA editing controlled cathepsin S (CTSS) mRNA translation in atherosclerosis by recruiting the stabilizing RNA-binding protein human antigen R (HuR) to CTSS 3′ UTR, thereby enhancing CTSS mRNA stability and translation." (PMID 37612540, 2023). "Cathepsin S inhibitors and siRNA targeting the regulation of CD74 function have also made progress in animal models of atherosclerosis or cardiac I/R injury." (PMID 36712241, 2022). "A total of 6 intersecting drugs targeting 3 genes, CSF1R, CTSS, and ITGB2, were selected as candidate druggable molecular targets for atherosclerosis." (PMID 35811739, 2022). "Studies in animal models and humans have demonstrated that CTSS, ITGB2, and TYROBP are markers for obesity and represent possible molecular links between obesity and obesity comorbidities, such as cardiovascular diseases and atherosclerosis." (PMID 37458462, 2023). "The expression of CTSS and CTSK (Cathepsin K) as well as their proteins in patients with atherosclerosis is significantly elevated, although the mechanism of CTSS in acute atherosclerotic cerebral infarction has not been studied yet." (PMID 30341237, 2018).
breast carcinoma (38 papers, 2011 to 2025). "CTSS expression is higher in patients with glioblastoma, breast cancer, and papillary thyroid cancer, associated with poorer prognosis." (PMID 40739397, 2025). "Visualization of the gene interaction network of cathepsin S revealed the degradation of occludin, which would result in the metastasis of cancer cells causing bone and breast cancers." (PMID 34827106, 2021). "Previous study found that inhibition of CTSS can cause the expression of ER stress-related proteins, as well as the increase of cytosolic Ca2+ in the renal cancer, lung cancer and breast cancer cell lines." (PMID 33425712, 2020). "Finally, increased expression of CTSS in the stromal cells revealed a significant association with ductal breast cancer (p<0.0001), though it is important to note that the study is underpowered to robustly assess any association with other histologies." (PMID 31346333, 2019). "Patient survival analysis using the KM Plotter database revealed that the reduced expression of Cathepsin S (CTSS) and DKK-1 are significantly associated with poor RFS of basal- like breast cancer patients." (PMID 41279138, 2025). "We found that AQP1 recruited ANXA2 to the Golgi apparatus, promoted Golgi apparatus extension, and induced secretion of ICAM1 and CTSS, which induced breast cancer cell invasion." (PMID 36803413, 2023). "AQP1 can also reside in the Golgi apparatus, where it can induce cell secretion of ICAM1 and CTSS, leading to the local invasion of breast cancer." (PMID 36803413, 2023). "Clinical experiments showed that cathepsin S (a protease that was usually expressed by leukocytes) mediated the migration of breast cancer cells through BBB." (PMID 36874630, 2023). "In line with previous studies, our study demonstrated that down-regulated CTSS inhibited breast cancer cells local invasion." (PMID 36803413, 2023). "High cathepsin S expression at the primary site correlated with decreased brain metastasis-free survival in breast cancer patients." (PMID 30669448, 2019). "To first investigate the role of CTSS expression in breast cancer, we applied IHC of CTSS on a tissue microarray (TMA) representing a cohort of 296 patients (hereafter referred to as BR300 cohort)." (PMID 31346333, 2019). "Pharmacological inhibition of CTSS significantly reduced experimental breast cancer metastasis and tumor development, suggesting its potential as a therapeutic target for this disease." (PMID 30006610, 2019). "From these data, we suggest that CTSS inhibition is a good strategy for functional restoration of BRCA1 in breast cancers with reduced BRCA1 protein stability." (PMID 30006610, 2019). "This led us to further investigate if the expression of epithelial-derived CTSS was specific to certain sub-types of breast cancer." (PMID 31346333, 2019). "Here, we carried out immunohistochemical (IHC) staining of CTSS using a breast cancer tissue microarray in patients who received adjuvant therapy." (PMID 31346333, 2019). "Following evaluation of CTSS protein expression and the association with survival using the BR300 patient cohort, we next wished to observe differential CTSS expression within breast cancer subtypes." (PMID 31346333, 2019). "This study highlights a need for further investigation into this protease within breast cancer, to consolidate the potential predictive and prognostic utility of CTSS expression in different subtypes." (PMID 31346333, 2019). "Recently, Sevenich and colleagues examined the role of CTSS in breast cancer progression, identifying a role for CTSS in breast-to-brain metastases via cleavage of JAM-B, a junctional adhesion molecule involved in blood-brain barrier transmigration." (PMID 31346333, 2019). "Spontaneously uced rat mammary tumors and human breast cancer tissues with high levels of CTSS expression showed low BRCA1 expression." (PMID 30006610, 2019).